U8 (U8 small nucleolar RNA )
Synonyms: LOC124900359
Gene: Small nucleolar RNA gene on chromosome 15 (30,112,198 to 30,112,330, forward strand). Ensembl gene ENSG00000207432.
Gene Ontology:
Biological process: RNA processing
Cellular component: nucleolus
Homologues: Orthologues: chimpanzee U8 (97% identical), rabbit U8 (53% identical). Paralogues in human: U8 (99% identical), U8 (97% identical), U8 (79% identical), U8 (77% identical), U8 (76% identical), U8 (75% identical), U8 (71% identical), U8 (69% identical), U8 (68% identical), U8 (66% identical), U8 (65% identical), U8 (44% identical).